PTPN23 (protein tyrosine phosphatase non-receptor type 23)
Description:
Plays a role in sorting of endocytic ubiquitinated cargos into multivesicular bodies (MVBs) via its interaction with the ESCRT-I complex (endosomal sorting complex required for transport I), and possibly also other ESCRT complexes. May act as a negative regulator of Ras-mediated mitogenic activity. Plays a role in ciliogenesis.
Synonyms: HD-PTP; PTP-TD14; KIAA1471; DKFZP564F0923; HDPTP; NEDBASS
Tractability: Small molecule: it has a binding pocket of medium quality. PROTAC: ubiquitination databases record sites on it; its protein half-life has been measured.
Gene: Protein-coding gene on chromosome 3 (47,381,011 to 47,413,442, forward strand). Ensembl gene ENSG00000076201.
Subcellular location: Nucleus; Cytoplasm; Cytoplasmic vesicle; Endosome; Cytoplasm, cytoskeleton, cilium basal body; Early endosome
Subcellular location (Human Protein Atlas): Basal body; Nuclear bodies; Nucleoplasm; Calyx; Centriolar satellite; Cytosol; Mid piece; Vesicles
Pathways (Reactome):
Immune System: Interleukin-37 signaling
Gene Ontology:
Molecular function: protein binding; protein kinase binding; protein tyrosine phosphatase activity
Biological process: cilium assembly; early endosome to late endosome transport; endocytic recycling; negative regulation of epithelial cell migration; positive regulation of adherens junction organization; positive regulation of early endosome to late endosome transport; positive regulation of homophilic cell adhesion; positive regulation of Wnt protein secretion; ubiquitin-dependent protein catabolic process via the multivesicular body sorting pathway
Cellular component: ciliary basal body; cytoplasm; cytosol; early endosome; endosome; extracellular exosome; nuclear body; nucleoplasm; nucleus; cytoplasmic vesicle
Genetic constraint (gnomAD): Loss-of-function variants: 74 observed, 155.5 expected, observed/expected ratio (o/e) 0.48, 90% interval 0.39 to 0.58. The upper end of that interval is the gene's LOEUF score, 0.58, which puts it in group 2 of 6, group 1 being the genes least tolerant of losing a copy. Missense variants: 1,959 observed, 2,176 expected, observed/expected ratio (o/e) 0.9, 90% interval 0.87 to 0.93. Synonymous variants: 949 observed, 897.81 expected, observed/expected ratio (o/e) 1.06, 90% interval 1 to 1.12.
Homologues: Orthologues: chimpanzee PTPN23 (99% identical), macaque PTPN23 (98% identical), pig PTPN23 (92% identical), rabbit PTPN23 (92% identical), dog PTPN23 (92% identical), mouse Ptpn23 (91% identical), rat Ptpn23 (91% identical), guinea pig PTPN23 (86% identical), tropical clawed frog ptpn23 (65% identical), zebrafish ptpn23a (61% identical), zebrafish ptpn23b (34% identical). Paralogues in human: PTPRS (15% identical), PTPRF (15% identical), PTPRD (14% identical), PTPRZ1 (13% identical), PTPRB (13% identical), PTPRT (12% identical), PTPN13 (12% identical), PTPRK (12% identical), PTPRM (12% identical), PTPRU (12% identical), PTPRG (11% identical), PTPN21 (11% identical), and 23 more.